PVALB (parvalbumin)
Diseases named in the same sentence as PVALB in open-access papers (continued):
Sharing a sentence is not in itself a finding about the gene and the disease.
thyroid (2 papers, 2011 to 2026). "The tumor expressed thyroid markers (TTF-1, PAX-8, thyroglobulin) and renal cell markers (colloidal iron, parvalbumin, CD117) with peripheral mitochondrial accentuation by anti-mitochondrial staining." (PMID 41518426, 2026).
viral infection (2 papers, 2019 to 2025). "Parvalbumin (PV) interneurons primarily form local cortical connections, indicating effective retrograde labeling without diffusive viral infection." (PMID 40089466, 2025).
age (1 paper, 2025). A temporal measurement of the time period elapsed since an identifiable point in the life cycle of an organism. "AHANK is also reported as a brain-associated marker for stress responses relating to parvalbumin-expressing interneurons, glutamatergic transmission, and post-synapse in chronic stress, as well as a marker for age-related neurodegeneration." (PMID 41488750, 2025).
age-related hearing loss (1 paper, 2020). "The authors test the question of whether the loss of parvalbumin inhibitory neurons that is seen in the C57BL/6 strain of mouse - a strain that suffers from age-related hearing loss - is caused by the hearing loss itself or is just a natural part of the aging process." (PMID 32327469, 2020).
amblyopia (1 paper, 2022). Decreased vision that results from abnormal visual development. "Specifically, amblyopia has been linked to increased numbers of active somatostatin positive interneurons, without any detectable effect on either vasointestinal protein or parvalbumin positive cells." (PMID 35558878, 2022).
asphyxia (1 paper, 2019). A state of general hypoxia and hypercapnia (abnormally elevated carbon dioxide (CO2) levels in the blood), resulting in acidosis, which affects all tissues in the body. "Loss of calbindin and parvalbumin immunopositive neurons from the striatum has also been reported after perinatal asphyxia." (PMID 31417418, 2019).
atopic dermatitis (1 paper, 2020). "67% (12/18) of the dogs with atopic dermatitis that had high levels of specific IgE to crude cod extract and tropomyosin did not have specific IgE to cod parvalbumin or collagen." (PMID 32938440, 2020).
Auditory hallucination (1 paper, 2023). Perception of sounds without auditory stimulus. "This phenomenon has been correlated with psychotic symptoms such as auditory hallucinations and could reflect the dysfunction of NMDA receptors on parvalbumin-expressing inhibitory interneurons." (PMID 37206313, 2023).
chromophobe carcinomas (1 paper, 2022). "CK7, S100A1, and parvalbumin are helpful immunohistochemical markers in the differential diagnosis between chromophobe renal cell carcinoma and TFE3/TFEB-rearranged renal cell carcinoma." (PMID 35980471, 2022). "Parvalbumin and CK7/S100A1 respectively are of paramount importance when TFE3/TFEB-rearranged renal cell carcinoma resembles oncocytoma and chromophobe renal cell carcinoma." (PMID 35980471, 2022). "Expression of CK7 and parvalbumin along with the absence of S100A1 is characteristic of chromophobe renal cell carcinoma, whereas strong and diffuse labeling of S100A1 along with the under-expression of CK7 and parvalbumin are typical of TFE3/TFEB-rearranged renal cell carcinoma." (PMID 35980471, 2022).
cognitive (1 paper, 2025). "Restoring parvalbumin interneuron hypomyelination in the medial prefrontal cortex rescues cognitive deficits." (PMID 40518508, 2025).
cortical dysplasia (1 paper, 2022). "A reduction in parvalbumin and somatostatin cells has been reported in human GG tissues, and this phenomenon was suggested to trigger hyperexcitability in an animal model of cortical dysplasia." (PMID 36538906, 2022).
demyelination (1 paper, 2021). "In an animal model of cortical demyelination, it has also been confirmed that the selective susceptibility of parvalbumin fast spiking interneurons are secondary to cortical demyelination." (PMID 34681255, 2021).
developmental delay (1 paper, 2021). "On the other hand, just as treatment with levothyroxine avoids developmental delay accompanying congenital hypothyroidism in humans, thyroid hormone replacement immediately after birth can prevent a decrease in the number of parvalbumin neurons in rodents." (PMID 34955723, 2021). "Therefore, a parvalbumin hypothesis for developmental delay has been proposed." (PMID 34955723, 2021).
diabetes mellitus (1 paper, 2021). A metabolic disorder characterized by abnormally high blood sugar levels due to diminished production of insulin or insulin resistance/desensitization. "Decreased levels of the calcium-binding protein parvalbumin in brain samples are also known to be associated with diabetes." (PMID 34639150, 2021). "The observed increase in parvalbumin expression after treatment with SeNP and/or M confirms their beneficial neurotherapeutic effects, accompanied by modulation of calcium homeostasis, which represents another possible pathway for the regulation of brain damage by SeNP caused by diabetes mellitus." (PMID 34639150, 2021).
dilated cardiomyopathy (1 paper, 2026). Cardiomyopathy which is characterized by dilation and contractile dysfunction of the left and right ventricles. "Surprisingly, we found RNA-binding motif protein 20 (RBM20), an alternative splicing regulator associated with dilated cardiomyopathy, to be expressed in cortical parvalbumin interneurons and mitral cells of the olfactory bulb." (PMID 41524378, 2026).
fibromyalgia (1 paper, 2021). A chronic disorder of unknown etiology characterized by pain, stiffness, and tenderness in the muscles of neck, shoulders, back, hips, arms, and legs. "Since patients with FM display elevated gamma oscillations in the pain matrix and parvalbumin (PV)-positive neurons play a critical role in induction of gamma oscillations, we hypothesized that changes in PV-positive neurons are involved in hyperalgesia in fibromyalgia." (PMID 35295447, 2021).
generalized epilepsy (1 paper, 2023). Epilepsy that is characterized by generalized seizure types and may have typical interictal and/or ictal EEG findings that accompany generalized seizure types (for example generalized spike-wave). "Also, axonal sprouting of SOM-INs and gain of dendritic inhibition associated with loss of parvalbumin synaptic inhibition in the CACNA1A mouse model of generalized epilepsy is reversed by rapamycin treatment and thus mTORC1-dependent." (PMID 37400913, 2023).
Hepatic steatosis (1 paper, 2022). Steatosis is a term used to denote lipid accumulation within hepatocytes. "Meanwhile, adiposity in BAT and scWAT, hepatic steatosis as well as plasma triglycerides (TAG) levels were also lower in parvalbumin blocker treated mice." (PMID 35676256, 2022).
Huntington disease (1 paper, 2010). Huntington disease (HD) is a rare neurodegenerative disorder of the central nervous system characterized by unwanted choreatic movements, behavioral and psychiatric disturbances and dementia. "In the brains of Huntington's disease patients, for example, and mice expressing mutant huntingtin protein, a large percentage of parvalbumin-positive neurons selectively degenerate." (PMID 20678225, 2010).
Hyperammonemia (1 paper, 2022). An increased concentration of ammonia in the blood. "It inhibits hyperexcitation during ischemia and hyperammonemia through the maintenance of the expression pattern of protective proteins, the calcium-binding protein parvalbumin, and the regulation of cytosolic calcium levels." (PMID 36555318, 2022).
hypothyroidism (1 paper, 2021). Abnormally low levels of thyroid hormone. "Animal experiments using hypothyroidism models display decreased parvalbumin expression and abnormal brain architecture, and these experimental results show reproducibility and stability." (PMID 34955723, 2021).
Insulin resistance (1 paper, 2022). Increased resistance towards insulin, that is, diminished effectiveness of insulin in reducing blood glucose levels. "Furthermore, treatment with parvalbumin blocker significantly lowered insulin levels and ameliorated insulin resistance in HFD-fed mice." (PMID 35676256, 2022).
ischemic stroke (1 paper, 2020). A stroke disorder caused by obstruction of blood flow to the brain, due to thrombotic (local blood clot formation) or embolic (due to a blood clot or other material traveling from another site) event. "Following ischemic stroke in monkey cortex, the NeuroD1-mediated astrocyte-to-neuron (AtN) conversion significantly increased local neuronal density, reduced microglia and macrophage, and surprisingly protected parvalbumin interneurons in the converted areas." (PMID 33224952, 2020).
leukodystrophy (1 paper, 2023). Leukodystrophies are a group of rare, progressive, metabolic, genetic diseases that affect the brain, spinal cord and often the peripheral nerves. "Together, these results indicate that interneurons are involved, possibly parvalbumin interneurons, in disease mechanisms of 4H leukodystrophy." (PMID 36729681, 2023).
Lysosomal disease (1 paper, 2017). "Calretinin is a calcium-binding protein, and in combination with parvalbumin and perineuronal nets can help identify and analyze the upgaze vs. downgaze ocular motor disturbances in other lysosomal diseases, such as Niemann–Pick disease type C." (PMID 29379464, 2017).
meningioma (1 paper, 2016). A generally slow growing tumor attached to the dura mater. "Autosomal genes that were comparably lower expressed in meningiomas from females included EPH receptor A3 (EPHA3), parvalbumin (PVALB), calbindin 2 (CALB2), and solute carrier family 38 member 3 (SLC38A3)." (PMID 27096627, 2016).
metastatic tumors (1 paper, 2024). "In terms of GO-MF, a large number of proteins were enriched in protein binding, among which parvalbumin may be the KICH marker that distinguishes primary from metastatic tumors (Section S3)." (PMID 38534453, 2024).
mood disorder (1 paper, 2021). A cognitive disorder a disturbance in which the person's mood is hypothesized to be the main underlying feature. "The parvalbumin-positive GABAergic interneurons in the hippocampus represent an especially vulnerable population of neurons in chronic stress, which might be of key importance in the development of mood disorders." (PMID 33510780, 2021).
motor neuron disease (1 paper, 2014). "As previously shown by immunoblotting and proteomics in the WR and SOD mouse models of ALS, respectively, the concentration of the cytosolic Ca2+-binding protein parvalbumin is drastically lowered in motor neuron disease." (PMID 24895011, 2014).
multiple sclerosis (1 paper, 2023). A progressive autoimmune disorder affecting the central nervous system resulting in demyelination. "In cerebrospinal fluid of multiple sclerosis patients, it was also found that the expression of parvalbumin was obviously decreased, along with severity of inflammation." (PMID 38157256, 2023).
muscle atrophy (1 paper, 2022). The loss of muscle tissue due to inactivity or disease. "We observed a significant decreased expression of parvalbumin mRNA during disease progression in SMA mice compared to WT animals, further confirming parvalbumin as a bona fide marker of muscle atrophy in SMA." (PMID 35902978, 2022).
neuropathic pain (1 paper, 2023). Chronic pain caused by damage to nerve fibers. "We investigated the effects of voluntary running (VR) on FosB+ cells and GABAergic interneurons (parvalbumin-positive [PV+] and somatostatin-positive [SOM+]) in the vHPC-CA1 in neuropathic pain (NPP) model mice." (PMID 36788313, 2023).
nicotine dependence (1 paper, 2021). Physical and psychological dependence on nicotine. "Our data suggest that striatal fast‐spiking parvalbumin interneurons mediate the behavioral effect of nicotine and sparse motor learning, the notions of which may be extended to the research for nicotine dependence and movement disorders." (PMID 32767546, 2021).
oncocytoma (1 paper, 2022). "Cathepsin K and parvalbumin are the two useful markers in the differential diagnosis between oncocytoma and TFE3/TFEB-rearranged renal cell carcinoma." (PMID 35980471, 2022).
periventricular leukomalacia (1 paper, 2019). Periventricular leukomalacia (PVL) is a brain injury disorder characterized by the death of the white matter of the brain due to softening of the brain tissue. "Another clinical study found significant lower parvalbumin-positive neuronal density in 10 of 11 patients with severe periventricular leukomalacia (PVL), which correlated with developmental impairment of thalamocortical connections." (PMID 31178744, 2019).
postpartum depression (1 paper, 2020). A type of clinical depression that occurs after childbirth. "Although dGABAAs in dentate GCs and in hippocampal parvalbumin-positive (PV+) interneurons have been implicated in postpartum depression, the brain regions regulating postpartum depression have not been identified directly in conditional δ KO mice." (PMID 33147470, 2020).
renal cell carcinoma (1 paper, 2022). "About parvalbumin expression, among 33 MiT family translocation renal cell carcinomas 12 (36%), using a 5% cutoff, and 7 (21%), both considering a 10% and 20% cutoff, labeled positive for it." (PMID 35980471, 2022). "Moreover, 7 of 10 (70%) and 2 of 10 (20%) TFEB-rearranged renal cell carcinomas revealed positive parvalbumin expression respectively considering a 5% threshold and both a 10% and a 20% threshold." (PMID 35980471, 2022). "A panel of immunohistochemistry markers useful to distinguish TFE3/TFEB-rearranged renal cell carcinoma from other common renal cell neoplasms should include cathepsin K, CA9, CK7, and parvalbumin." (PMID 35980471, 2022). "As for the distal tubular markers such as GATA3 and parvalbumin, none of the MiT family translocation renal cell carcinomas retrieved was positive for the former." (PMID 35980471, 2022). "In conclusion, since TFE3/TFEB-rearranged renal cell carcinoma may mimic several histotypes, an immunohistochemical panel to differentiate them from common renal cell tumors should include cathepsin K, CA9, CK7, and parvalbumin." (PMID 35980471, 2022).
renal oncocytomas (1 paper, 2009). "Markers such as cytokeratin 7, parvalbumin or claudin 7 were found to be expressed in the majority of chromophobe RCCs, but rarely in renal oncocytomas." (PMID 19445733, 2009).
retinal degeneration (1 paper, 2024). Degeneration of the retina. "Here, we investigated if changes in cortical functioning is linked to alterations in GABAergic population of neurons and its two important subsets, somatostatin (SST) and parvalbumin (PV) neuron in rd1 model of retinal degeneration (RD)." (PMID 39444393, 2024).
retinal ischemia (1 paper, 2023). A ischemic disease that involves the retina. "Previous studies have found that the expression of PVALB was decreased after the induction of retinal ischemia/reperfusion in rats, ONC in rats, and chronic elevation of IOP in mice." (PMID 37901418, 2023).
sarcopenia (1 paper, 2019). Progressive decline in muscle mass due to aging which results in decreased functional capacity of muscles. "Other studies with mammals have shown that PVALB levels in muscle are reduced in senescence-related sarcopenia and increased after exercise." (PMID 31856193, 2019).
scoliosis (1 paper, 2020). A congenital or acquired spinal deformity characterized by lateral curvature of the spine. "The observed difference in spine malalignment, namely C-shaped scoliosis exhibited by PValb-Cre;Piezo2f/f mice, as compared with an S-shaped scoliosis in Runx3 and Egr3 KO mice, indicates a variance in severity among genotypes." (PMID 32576830, 2020). "Interestingly, whereas PValb-Cre; Piezo2f/f spines exhibited a C-shaped scoliosis, i.e. one curvature, Runx3 and Egr3 KO mice exhibited an S-shaped, two-curvature scoliosis." (PMID 32576830, 2020).
sexual dysfunction (1 paper, 2014). Disturbances in sexual desire and the psychophysiologic changes that characterize the sexual response cycle and cause marked distress and interpersonal difficulty. "A genome wide association study found a correlation between a SNP in the PVALB gene and female sexual dysfunction." (PMID 24548546, 2014).
spinal cord injury (1 paper, 2023). Penetrating and non-penetrating injuries to the spinal cord resulting from traumatic external forces (e.g., WOUNDS, GUNSHOT; WHIPLASH INJURIES; etc.). "This study aimed to investigate the effect of perineuronal net (PNN) and neurocan (NCAN) on spinal inhibitory parvalbumin interneuron (PV‐IN), and the mechanism of electroacupuncture (EA) in promoting spinal cord injury (SCI) repair through neurocan in PNN." (PMID 37950551, 2023).
thyroid nodule (1 paper, 2011). A small circumscribed mass in the THYROID GLAND that can be of neoplastic growth or non-neoplastic abnormality. "We identified PVALB as a new marker that can be used in combination with C1orf24 and ITM1 for a more accurate diagnosis of thyroid nodules." (PMID 22654558, 2011).
tonic-clonic seizures (1 paper, 2021).
Tremor (1 paper, 2021). An unintentional, oscillating to-and-fro muscle movement about a joint axis. "A recent study showed that the deletion of synaptotagmin-2 (Syt2) from excitatory parvalbumin positive neurons in cerebellar nuclei produced asynchronous transmitter release and action tremor in mice." (PMID 33804860, 2021).
tuberous sclerosis (1 paper, 2013). Hereditary disease characterized by seizures, intellectual disability, developmental delay, and skin and ocular lesions. "Abnormal inhibitory circuits in cortical tubers of tuberous sclerosis, associated with refractory epilepsy, are accompanied by aberrant expression of parvalbumin and calbindin D28k in the dysplastic cortex." (PMID 23883617, 2013).
vitamin D deficiency (1 paper, 2022). A nutritional condition produced by a deficiency of VITAMIN D in the diet, insufficient production of vitamin D in the skin, inadequate absorption of vitamin D from the diet, or abnormal conversion of vitamin D to its bioactive metabolites. "Secondly, it should be noted that the impact of vitamin D deficiency is not limited to PNN reduction but may cause changes in gene expression by the genomic actions of vitamin D. For example, vitamin D can directly regulate the gene expression of parvalbumin." (PMID 35207806, 2022).